ZMYND12 (zinc finger MYND-type containing 12)
Description:
Required for sperm flagellum function and male fertility.
Synonyms: DKFZp434N2435
Tractability: Small molecule: a structure with a bound ligand is known.
Gene: Protein-coding gene on chromosome 1 (42,430,329 to 42,456,253, reverse strand). Ensembl gene ENSG00000066185.
Subcellular location: Cell projection, cilium, flagellum
Subcellular location (Human Protein Atlas): Nucleoplasm; Cytosol
Gene Ontology:
Molecular function: protein binding
Biological process: flagellated sperm motility; sperm axoneme assembly; sperm capacitation
Cellular component: sperm flagellum; motile cilium
Genetic constraint (gnomAD): Loss-of-function variants: 30 observed, 39.29 expected, observed/expected ratio (o/e) 0.76, 90% interval 0.57 to 1.04. The upper end of that interval is the gene's LOEUF score, 1.04, which puts it in group 4 of 6, group 1 being the genes least tolerant of losing a copy. Missense variants: 408 observed, 438.94 expected, observed/expected ratio (o/e) 0.93, 90% interval 0.86 to 1.01. Synonymous variants: 144 observed, 166.49 expected, observed/expected ratio (o/e) 0.86, 90% interval 0.75 to 0.99.
Homologues: Orthologues: chimpanzee ZMYND12 (99% identical), macaque ZMYND12 (97% identical), guinea pig ZMYND12 (85% identical), dog ZMYND12 (84% identical), pig ZMYND12 (82% identical), mouse Zmynd12 (81% identical), rat Zmynd12 (77% identical), rabbit ZMYND12 (74% identical), tropical clawed frog zmynd12 (49% identical), zebrafish zmynd12 (35% identical). Paralogues in human: PDCD2L (12% identical), PDCD2 (11% identical).
Diseases named in the same sentence as ZMYND12 in open-access papers:
ZMYND12 is named in the same sentence as 2 diseases in open-access papers, as found by Europe PMC text mining. Sharing a sentence is not in itself a finding about the gene and the disease. The quoted sentences say what the papers report.
infertile (2 papers, 2023 to 2024). "ZMYND12 deficiency has previously been tied to infertility in males, yet the underlying mechanism remains uncertain." (PMID 39066891, 2024). "Here, from whole-exome sequencing on samples from 168 infertile men with asthenoteratozoospermia due to severe sperm flagellum, we identified homozygous ZMYND12 variants in four unrelated patients." (PMID 37934199, 2023).
ZMYND12 also shares sentences with these, for which no sentence is quoted: male infertility (1 paper).